EGFR (epidermal growth factor receptor)
Diseases named in the same sentence as EGFR in open-access papers (continued):
Sharing a sentence is not in itself a finding about the gene and the disease.
gastric cancer (continued). "For the inhibition of PKG II on EGF/EGFR induced MAPK/ERK-mediated signal transduction pathway, our previous work have shown that PKG II inhibits the activation of all key components in the pathway induced by EGF in gastric cancer cell line BGC-823." (PMID 23613900, 2013). "No studies on this therapeutic strategy for gastric cancer have been reported previously, so the present study is the first to report that a EGFR/CD3 BsAb is able to enhance the cytotoxicity of CIK cells to gastric cancer cells in vitro and in vivo." (PMID 23833649, 2013). "Based on our results, it is possible that via the upregulation of Cyclin D1, EGFR, Bcl-2, MMP-9 and MMP-2 expression and MVD, CXCR1/2 and their ligands are involved in mediating proliferation, growth, angiogenesis, invasion and metastasis of gastric carcinoma." (PMID 23420470, 2013). "Although EGFR is not a prognostic factor in metastatic gastric cancer, this is not a reflection on its value as a predictive marker." (PMID 23153332, 2012). "This study evidences previously observed perturbations of the KRAS, ERBB2, EGFR, MET, PIK3CA, FGFR2 and AURKA genes in gastric cancer and suggests some of the targeted therapies approved or in clinical development would be of benefit to 11 of the 50 patients studied." (PMID 21781349, 2011). "EGFR and ERBB2 expression in gastric epithelial cells are indicators of malignancy and may prove useful as markers for poor prognosis in gastric cancer." (PMID 21689422, 2011). "EGFR and ERBB2 expression in gastric cancer has been reported in many past studies." (PMID 21689422, 2011). "We have previously shown that certain CDH1 mutations have a negative influence on survival of gastric carcinoma patients and that CDH1 mutations are associated with enhanced EGFR activation." (PMID 22152101, 2011). "Recently, we demonstrated that p37 may promote gastric cancer cell invasion and metastasis by increasing the activity of MMP-2 and by inducing EGFR phosphorylation, therefore contributing to tumor metastasis upon Mycoplasma hyorhinis infection." (PMID 21062494, 2010). "Although colorectal tumours with an activating mutation of the Kirsten(K)-ras gene are not sensitive to EGFR antibodies, the incidence of KRAS mutations in gastric cancer appears to be low." (PMID 20068568, 2010). "In conclusion, high expression of EGFR might be a good predictive marker of relapse and survival in curatively resected stage III–IV (M0) gastric cancer patients who received adjuvant 5-FU and cisplatin chemotherapy." (PMID 19259093, 2009). "In the past, high levels of EGFR were reported as a poor prognostic factor for overall survival (OS) in resectable gastric cancer patients who did not receive chemotherapy." (PMID 19259093, 2009). "Therefore, it is reasonable to focus on EGFR, HER2, and TOP2A overexpression and/or gene amplification when developing therapeutic strategies to target gastric carcinomas." (PMID 19061514, 2008). "The correlation between EGFR, HER2, and TOP2A in gastric carcinomas was determined." (PMID 19061514, 2008). "We developed three new HER2-overexpressing gastric cancer cell lines (GLM-1, GLM-2, GLM-4) without epidermal growth factor receptor (EGFR) mutations derived from such liver metastasis, two of which had HER2 gene amplifications." (PMID 17088902, 2006). "The RAS-RAF-MEK-ERK pathway (downstream of EGFR) could be activated by a low MED12 induced TGF-βR signaling pathway, suggesting that the EGFR Inhibitor would not be effective for advanced gastric cancer with a high-risk score." (PMID 38467827, 2024).
gastric cancer (continued). "Bombyx mori carboxypeptidase inhibitor can inhibit the rapid proliferation of gastric cancer cells induced by the addition of EGF, which indicates that the inhibitory activity of silkworm carboxypeptidase inhibitor is likely related to the downstream-related pathways initiated by EGF/EGFR." (PMID 36674593, 2023). "In gastric cancer cells, the RANKL/RANK pathway can abrogate cetuximab sensitivity by phosphorylation of EGFR, AKT, and ERK, whereas ΔNp63α expression can increase EGFR mRNA, total EGFR protein, and phospho-EGFR (Y1086), thus contributing to tumor cell proliferation." (PMID 35205415, 2022). "In contrast, the EGFR-targeting antibody cetuximab failed to improve survival in the randomised international Erbitux (cetuximab) in combination with Xeloda (capecitabine) and cisplatin in advanced esophago-gastric cancer (EXPAND) study." (PMID 35264144, 2022). "Therefore, EGFR targeted NIR-PIT, perhaps in combination with HER2 targeted NIR-PIT might be a suitable treatment for some patients with gastric cancer." (PMID 36405499, 2021). "Although targeting EGFR in gastric cancer has been evaluated extensively and shown to be not efficacious, we have recently demonstrated targeting ctDNA-based EGFR amplifications may be a novel target of interest." (PMID 32850413, 2020). "Moreover, upregulation of GHET1 could be induced by hypoxia in gastric cancer cells, and the depletion of GHET1 c significantly enhanced the CpG island methylation of EGFR, which plays a crucial role in the metastasis of cancers." (PMID 32280301, 2020). "Therefore, our findings uncover the contexts in which a recognized cytoskeletal protein MICAL‐L2 functions to keep EGFR content and selective inhibition of MICAL‐L2 may represent a new potential target for gastric cancer metastasis therapy." (PMID 31034158, 2019). "We analyzed the expression level of gastric cancer-related genes EGFR, FGFR2, KLF4, DNMT1 and AGO4 identified through bioinformatics screening by relative quantification method and observed differential expression of EGFR, FGFR2, KLF4, DNMT1 and AGO4 in tumors." (PMID 29719612, 2018). "As in cervical and gastric cancer, SNAIL expression in DFSP may be promoted by EGFR signaling." (PMID 29492209, 2018). "We previously reported that high levels of tyrosine kinase receptor (RTK) gene amplification of EGFR, HER2, FGFR2, or MET had protein overexpression and rarely showed other coexisting gene alterations using the next-generation sequencing (NGS) method for gastric cancer." (PMID 28852882, 2018). "Although EGFR may not be beneficial for the survival of patients with gastric cancer, they were found to have significant predictive ability for the prognosis of patients." (PMID 28460479, 2017). "Although relatively few gastric cancer cases have been evaluated, one report demonstrated that IGFIR overexpression in a primary tumor was correlated with increased lymph node metastasis, and that patients with low expression of both IGF1R and EGFR had significantly improved OS." (PMID 26884344, 2017). "We have demonstrated that ACh could act though M3R to activate EGFR pathway, while knockdown M3R or inhibiting EGFR could reverse the cell proliferation and phosphorylation of ERK and AKT induced by ACh stimulation in gastric cancer." (PMID 28102288, 2017). "The stimulation of proliferation in the gastric carcinoma GXF251L cell line could not be attributed to the classical activation of the EGFR and/or ERK 1/2 signaling pathways, usually reflected by enhanced phosphorylation." (PMID 28336852, 2017). "Thus, it is reasonable that GL-1196 suppressed the PAK4/c-Src/EGFR/cyclinD1 pathway and CDK4/6 expression, which, in turn, inhibited the transition of cells from G1 to S phase, and finally resulted in the anti-proliferative effect on gastric cancer cells." (PMID 27077843, 2016). "Therefore, application of EGFR and VEGFR molecular targeted drugs may provide a new direction for treatment of advanced gastric cancer." (PMID 27633381, 2016).
gastric cancer (continued). "The failure of the EXPAND and REAL3 trials suggested that EGFR may not be the primary oncogenic driver in advanced gastric cancer." (PMID 26728266, 2016). "Therefore, anti-EGFR and anti-VEGFR target drugs for the treatment of advanced gastric cancer may be of great significance." (PMID 27633381, 2016). "In this study, adding HGF to lapatinib treatment in MET-overexpressed HER2 gastric cancer cells not only activated MET, but also led to restimulation of downstream effectors AKT and ERK1/2 even in the presence of lapatinib, although phosphorylation of HER2 and EGFR continued to be suppressed." (PMID 26716644, 2016). "Of the studies using FISH to evaluate EGFR copy number change or amplification, two were in gastric cancer patients, demonstrating poor survival in the 4.88 % of European patients with amplification, however survival outcome was not assessed in 29 % EGFR amplified Chinese gastric cancer patients." (PMID 26478746, 2015). "In a clinical setting, when erlotinib, an oral EGFR inhibitor, was administered to metastatic or unresectable cases of gastro-esophageal (GE) junction and gastric adenocarcinomas in SWOG0127 trials 31, more cases of GE junction cancer than of gastric cancer responded clinically." (PMID 25154973, 2015). "Moreover, cMet-overexpressing gastric cancer cells can acquire resistance to therapy targeted against the HER family, such as epidermal growth factor receptor-2 (Her2) and the epidermal growth factor receptor (EGFR)." (PMID 25638174, 2015). "Differences in the studies may be due to the lack of a standard evaluation of EGFR expression in patients with gastric cancer." (PMID 24348859, 2014). "Conversely, the EGFR/HER-2/KRAS pathway has never been investigated in canine gastric cancer." (PMID 24454858, 2014). "Correlation analysis between CXCR1/2 and pAKT (P=0.032), pERK (P<0.001), Cyclin D1 (P=0.049), EGFR (P=0.013), Bcl-2 (P=0.003), microvessel density (P=0.001), MMP-9 (P=0.013) and MMP-2 (P=0.027) expression using the Spearman test showed significant correlation in gastric carcinoma." (PMID 23420470, 2013). "However, a lack of reliable and accurate methods to assess the relationship between EGFR and ERBB2 gene status and protein expression in gastric cancer has limited correlative assessments with clinical parameters, including survival and sensitivity to targeted agents." (PMID 21689422, 2011). "The activation of EGFR could have an important role for the cell proliferation and the inhibition of apoptosis, indicating that the SN38-induced activation of the EGF/EGFR may be involved in the resistance of gastric cancer cells to irinotecan." (PMID 21997136, 2011). "Moreover, targeted therapies have recently made their way in gastric cancer with the approval of trastuzumab for the treatment of HER-2 positive metastatic gastric cancer Anti-angiogenics (bevacizumab) and anti-EGFR agents (cetuximab) are also being studied in the adjuvant setting." (PMID 20525367, 2010). "Dual inhibitor of EGFR and HER2 may be benefit to patients with gastric carcinoma." (PMID 19061514, 2008). "We were unable to determine a relationship between the alterations in EGFR, HER2, TOP2A, chromosome 7, or chromosome 17 and the clinicopathologic characteristics of gastric carcinoma; this is in contrast to previous reports, and may be due to different sample numbers and different populations." (PMID 19061514, 2008). "Moreover, cetuximab therapeutically blocks EGFR, and this might concurrently induce the activation of IGF-1R, which could activate EGFR-downstream Akt signaling, thus mediating cetuximab resistance in gastric cancer cells." (PMID 37519889, 2023).
gastric cancer (continued). "We have also recently shown that MICAL-L2 attenuates lysosome-mediated EGFR degradation and enhances the migratory ability of gastric cancer cells, suggesting that MICAL-L2 functions to prevent the degradation of its client proteins and may play an oncogenic role in gastric cancer." (PMID 33520979, 2020). "Differing classification systems for significant copy number gain or amplification, distinct biological differences between gastric cancer and EC, and some studies not assessing correlation between EGFR copy number and survival may account for reported disparities." (PMID 26478746, 2015). "Phase II clinical trials evaluating monotherapies directed at other targets such as EGFR have shown limited efficacy in gastric cancer, with no current treatments targeted at RTKs approved in HER2-negative gastric cancer." (PMID 38791602, 2024). "Several meta-analyses already reported that anti-EGFR combination therapy did not improve PFS and OS in patients with esophago-gastric cancers." (PMID 29228748, 2017). "We previously reported that EGFR positivity, but not HER2 positivity, was associated with poor patient outcomes after curative resection of stage II/III gastric cancer, using archived specimens obtained from patients enrolled in the ACTS-GC." (PMID 25112781, 2015). "The distinct biological and molecular features of gastric cancer and EC, in particular the different frequencies of gene copy number changes, as well as the lack of a validated classification system for significant EGFR copy number gain or amplification, may account for inconsistencies in results." (PMID 26478746, 2015). "The present study indicated that SN38 upregulated the expression levels of EGFR and HER2 in SN38-resistant gastric cancer cells, but not parent cells." (PMID 21997136, 2011). "However, this hypothesis needs to be clarified by further studies, since we did not verify a statistically significant correlation between EGFR alterations and invasion in the gastric wall (p = 0.4642), as we have just analised a very low number of early gastric carcinomas (n = 2) in our series." (PMID 18199332, 2008). "In contrast, the TKI Lapatinib targeting both EGFR and HER2 did not improve clinical outcome in phase III studies for stage IV HER2+ gastric cancer patients in combination with standard chemotherapy compared to chemotherapy alone, in either first-line or second-line therapy." (PMID 34680363, 2021). "Conversely, previous reports have shown that EGFR directly interacts with CD44,32,33 although we could not reproduce this interaction in our gastric cancer PDCs (unpublished observations)." (PMID 31607750, 2019). "In particular, T cells precisely and efficiently expressed EGFR-CAR lysed EGFR+ NSCLC H23 and H460 cells but not EGFR-negative gastric cancer HGC27 cell line, indicating that these re-engineered T cells acquired specific cytolytic activity against EGFR+ tumor cells." (PMID 29415996, 2018). "They demonstrated that co-culture of LMP1-positive and -negative gastric cancer cells leads to elimination of LMP1-positive cells, through the release of LMP1-loaded exosomes that mediate epidermal growth factor receptor (EGFR) activation in LMP1-negative cells." (PMID 29675003, 2018). "Although two phase III trials (LOGiC and TyTAN) for lapatinib, which is an EGFR and HER2 kinase inhibitor, failed to reach the primary endpoint, lapatinib did show modest single-agent activity in advanced/metastatic gastric cancer patients with a response rate of 9%." (PMID 24612546, 2014). "Moreover, the combination of an EGFR inhibitor and SN38 synergistically suppressed cell growth and induced apoptosis in the SN38-resistant gastric cancer cell lines, OCUM-2M/SN38 and OCUM-8/SN38, but not in OCUM-2M and OCUM-8 cells." (PMID 21997136, 2011).
metastatic colorectal cancer (676 papers, 2006 to 2026). "Inhibition of the epidermal growth factor receptor (EGFR) shows clinical benefit in metastatic colorectal cancer (CRC) patients, but KRAS-mutations are known to confer resistance." (PMID 40329096, 2025). "For instance, KRAS/NRAS mutations in metastatic colorectal cancer (mCRC) are associated with resistance to EGFR-targeted therapies, such as cetuximab and panitumumab." (PMID 40740242, 2025). "A combination of encorafenib (a BRAF inhibitor) and cetuximab (an EGFR inhibitor) has been shown in clinical trials to improve survival in patients with metastatic colorectal cancer harboring the BRAF V600E mutation." (PMID 38888919, 2024). "Microsatellite-stable BRAF-mutated metastatic colorectal cancer patients treated with anti-EGFR/BRAF combinations had better responses and survival outcomes when RNF43 was mutated compared with wild-type cases." (PMID 39452477, 2024). "The objective of this study was to evaluate the predictive value of 18F-fluorodeoxyglucose [18F]FDG positron emission tomography (PET-CT) radiomic parameters in relation to KRAS/BRAF/EGFR mutations in patients with metastatic colorectal cancer (mCRC)." (PMID 39722096, 2024). "Certain genetic alterations and right-sided primary tumor location are associated with resistance to anti-epidermal growth factor (EGFR) treatment in metastatic colorectal cancer (mCRC)." (PMID 38347302, 2024). "Clinically, HER2 amplification has been linked to resistance to anti-EGFR therapies in metastatic colorectal cancer." (PMID 38790167, 2024). "The present study underscores the significance of [18F] FDG PET-CT radiomic parameters, particularly SUVmax, in their association with KRAS, BRAF, and EGFR mutations in metastatic colorectal cancer patients." (PMID 39722096, 2024). "The immunoglobulin G1 monoclonal antibody against the EGFR, cetuximab (Erbitux), is associated with improved overall survival and progression-free survival in patients with metastatic colorectal cancer (mCRC)." (PMID 39618678, 2024). "KRAS mutations in metastatic colorectal cancer (mCRC) are used as predictive biomarkers to select therapy with EGFR monoclonal antibodies (mAbs)." (PMID 38402342, 2024). "Cetuximab is a therapeutic agent considering that EGFR is higher expressed in metastatic colorectal cancer (mCRC) and associated with cancer development and progression." (PMID 36668877, 2023). "BRAF mutations, particularly the V600E mutation, in metastatic colorectal cancer are associated with a poor prognosis and reduced response, especially when treated with EGFR inhibitors." (PMID 37686423, 2023). "Activating RAS gene mutations occur in approximately 55% of patients with metastatic colorectal cancer (mCRC) and are associated with poorer clinical outcomes due to epidermal growth factor receptor (EGFR) blockade resistance." (PMID 37597246, 2023). "Cell-free DNA RAS mutation is being increasingly monitored in metastatic colorectal cancer (mCRC) for disease molecular characterization and selecting eligible patients for anti-EGFR initiation and rechallenge." (PMID 36551560, 2022). "A BRAF inhibitor is currently approved in combination with the anti-EGFR monoclonal antibody cetuximab for second line treatment of metastatic colorectal cancers with BRAF mutations." (PMID 36079062, 2022). "HER2 amplification occurs in 2–6% of metastatic colorectal cancers and is associated with a poor response to EGFR antibody treatment." (PMID 35267469, 2022). "RAS mutations are present in approximately half of all metastatic colorectal cancer, and they greatly limit the therapeutic efficacy of anti-epidermal growth factor receptor (EGFR) antibodies, such as cetuximab." (PMID 35151318, 2022). "Anti-epidermal growth factor receptor (EGFR) monoclonal antibodies are approved for the treatment of RAS wild-type (WT) metastatic colorectal cancer (mCRC), but the emergence of resistance mutations restricts their efficacy." (PMID 35915157, 2022).